IL17A (interleukin 17A)
Diseases named in the same sentence as IL17A in open-access papers (continued):
Sharing a sentence is not in itself a finding about the gene and the disease.
tumor (continued). "In an azoxymethane (AOM)/ dextran sodium sulfate (DSS)-induced cancer-associated colitis model, complement deficiency was shown to inhibit intestinal IL-1β production by neutrophils and IL-17A production by myeloid cells, and to repress tumor formation." (PMID 32635472, 2020). "Whereas, other studies revealed that IL-17A can enhance the tumor killing capability via humoral cell-mediated induction of immunogenic antibody and cytolytic molecules in ESCC." (PMID 32298379, 2020). "Tumor-derived IL-1β induces γδ T cells to produce IL-17A and granulocyte-colony stimulating factor (G-CSF), which results in the recruitment of immunosuppressive neutrophils to the lung." (PMID 32849639, 2020). "Of note, PM2.5-enhanced tumor growth was clearly abrogated in IL-17a-/- mice; however, this effect was restored when IL-17a was again injected to mice." (PMID 32554855, 2020). "It is well-established that IFNγ- and Il-17A-producing effector T helper cells, called Th1 and Th17 respectively, are dominant modulators/effectors that provide anti-tumor activity." (PMID 33042110, 2020). "These mice contained low levels of IL-23 and upregulated IL-17A in the colon mucosa; tumor formation and intratumoral IL-23 expression were observed to be restored in environments with overexpression of IL-6." (PMID 32357539, 2020). "Meanwhile, immune response to the tumor was enhanced by promoting tumor-infiltrating M1 macrophages in the spleen, which secreted higher levels of IL17A in the spleen and TNF-α in the tumor." (PMID 31775255, 2019). "Both the B16 melanoma and Pts4d/d NSCLC models show that anti-tumor immunity mediated by IL17A is enhanced by the recruitment of dendritic cells (DCs)." (PMID 31921642, 2019). "IL17A can recruit CD103+ DCs which are critical for the anti-tumor function of CD8+ T cell in Pts4d/d mice." (PMID 31921642, 2019). "These tumor spheres were treated with recombinant IL-17A, C or F, and then analyzed for chemokine expression by q-RT-PCR." (PMID 31775909, 2019). "Then, the production of different cytokines (IFN-γ, IL-4, TNF-α and IL-17-A) by peripheral immune cells was evaluated at different time points after tumour irradiation." (PMID 31906092, 2019). "CCL20 preferentially mediates the recruitment of Th17 cells to tumor tissues, resulting in increased IL-17A secretion." (PMID 31387598, 2019). "Accumulating evidences shows that activation of the IL-17a/JAK2/STAT3 signalling pathway by growth factors or cytokines plays an active role in tumor growth and progression." (PMID 30616627, 2019). "A similar correlation analysis was performed, and a positive correlation was observed between the protein levels of CCL20 and IL-17A in tumor tissues (r = 0.361, p = 0.0025)." (PMID 31387598, 2019). "The levels of IL-17A secreted by tumor infiltrated γδ T cells of OC tissues (n = 15) was higher than that of peripheral blood (n = 10)." (PMID 31064389, 2019). "This interpretation is compatible with early reports linking IL-17A in LSCC to tumor angiogenesis and metastasis." (PMID 31885577, 2019). "In human CRC, chemotherapy led to the enrichment of IL-17A-producing CAFs within the tumor stroma, which in turn promoted the self-renewal of CSCs and tumor growth." (PMID 31417869, 2019). "In the present study, we found that an IL-17a neutralizating antibody partly suppressed the JAK2 or STAT3 phosphorylation, which suggested that IL-17a partially contributed to the tumor-promoting effects of TANs on GC cells." (PMID 30616627, 2019). "To date, however, we are not aware of completed clinical trials which have focused on the administration of MAbs targeting either IL17A or its receptor as a potential strategy to enhance the efficacy of anti-tumor chemotherapy and/or ICI-based immunotherapy." (PMID 31616428, 2019).
tumor (continued). "TANs are known to secrete multiple growth factors and chemokines such as TNFα, CCL2, IL-8, and IL-17a into the tumor microenvironment, where they promote the growth and invasion of the underlying tumor by triggering multiple pathways." (PMID 30616627, 2019). "IFN-γ is an active conventional cytokine in anti-tumor immunity, while IL-17A is conversely considered to promote immunosuppression and participate in tumor immune escape." (PMID 31064389, 2019). "They found that IL-17A rs2275913 polymorphism conferred susceptibility to CRC and was associated with tumor location and tumor differentiation." (PMID 31682719, 2019). "Interleukin-17A (IL-17A), a Th17 cell-secreted inflammatory cytokine, has been shown to have conflicting roles in regulating tumor development of EC." (PMID 31771653, 2019). "Consistent with the role of Tregs in limiting tumor-associated inflammation, blockade of CTLA-4 signaling by antibody increased the expression of IL-17A in tumors." (PMID 31775909, 2019). "Interleukin 17A (IL17-A) is classified as an anti-tumor response related cytokine and Interleukin 10 (IL-10) is characterized as an anti-inflammatory cytokine." (PMID 31533251, 2019). "A significantly higher expression of IL-17A in tumor tissues of PTC patients with coexistent HT was identified (P < 0.05)." (PMID 31159823, 2019). "Blocking IL-6 or Ly-6G showed reduced tumor burden than anti-PD-1 treatment in high IL17A lung tumors." (PMID 31921642, 2019). "TH17 cells, on the other hand, produce IL-17A, IL-17F, IL-21, and IL-22, which promote tumor growth by favoring antimicrobial tissue inflammation." (PMID 31906017, 2019). "Results are as follows, The high expression of NRP1 in the A549RR group boosted the mRNA and protein levels of IL-17A and IL-6 in tumor tissue, respectively." (PMID 31417646, 2019). "Strikingly, in contrast to the K-ras model, the Pts4d/d model with Il17a−/−, shows increased tumor burden and metastasis." (PMID 31921642, 2019). "With respect to pro-tumorigenic activity, IL-17A, which is produced not only by Th17 cells, but also by tumor cells per se, has been identified as a major offender." (PMID 31616428, 2019). "Immune competent Pts4d/d mice lacking I117a showed accelerated tumor progression and metastasis, indicating that IL17A plays a beneficial role in anti-tumor responses." (PMID 31921642, 2019). "CCL20 was highly expressed in the cytoplasm of tumor cells, and IL-17A was mainly from infiltrating lymphocytes." (PMID 31387598, 2019). "It has been found that IL-17A plays an important role in the development of various tumours, for example, breast cancer, hepatocellular carcinoma, and cervical cancer." (PMID 29955610, 2018). "In turn, activated mast cells release interleukin (IL)-17A, which can promote tumor cell proliferation and suppress its apoptosis in vitro." (PMID 30305610, 2018). "The same duality has been observed in other tumor types making IL-17 a “double-edged sword” in oncology." (PMID 30518157, 2018). "As both the HCCLM6 and Huh7 cells were labelled with GFP, we examined the number of circulating tumour cells (CTCs) from whole‐blood samples by flow cytometry and found that IL‐17A stimulation significantly increased the number of CTCs." (PMID 29689643, 2018). "To evaluate the effects of IL‐17A on in vivo metastasis, we established an orthotopic implantation tumour model to test HCC cell invasion and metastasis." (PMID 29689643, 2018). "Interleukin‐17A (IL‐17A), the production of which characterizes a subset of CD4+ helper T cells (Th17 cells), has been implicated in certain tumours, affecting tumorigenesis, proliferation and angiogenesis." (PMID 29689643, 2018). "Collectively, based on our in vitro and in vivo data, we propose a model involving complex interactions between ADM, mast cells, IL-17A and tumor cells within GC." (PMID 30305610, 2018). "We demonstrated that tumor infiltrated lymphocytes (TIL) isolated from BC biopsies secreted pathophysiological IL-17A." (PMID 30518157, 2018).
tumor (continued). "Inhibition of IL-17A changed the balance of T cells within the tumor and the expression of other cytokines." (PMID 29447258, 2018). "Similar results were seen in human CRC where a predominately Vδ1+ IL-17A-producing γδ T cell population positively correlated with a more advanced tumor stage." (PMID 30538697, 2018). "Collectively, these studies implicate tissue resident Vδ1+ and Vγ2+ T cells as tumor growth promoting through IL-17A-mediated MDSC recruitment and immunosuppression in cancer." (PMID 30538697, 2018). "While Vδ1 from peripheral blood were cytotoxic for colon cancer cells, an IL-17A-producing subset of Vδ1 cells promoted tumor growth." (PMID 29937769, 2018). "Consistent with our previous results, Id2 overexpressing Treg cells showed higher IL-17A expression in TILs and dLN of Dox-treated tumor bearing mice." (PMID 30413714, 2018). "A pro-tumor role of IL-17A-producing γδ T cells is evident in a number of cancers such as SCC, CRC, and metastatic breast cancer." (PMID 30538697, 2018). "Overall, the present study demonstrated that impact of Ki-67 LI and IL-17A on PA invasiveness, recurrence, and tumour growth type requires further investigation with increased sample sizes to confirm the association of Ki-67 LI and IL-17A in patients with PA." (PMID 29955610, 2018). "In our study, we further demonstrated that such tumor growth was through IL-17A from mast cells as blocking IL-17A reversed such growth." (PMID 30305610, 2018). "Previously, we demonstrated that IL‐17A was associated with HCC prognosis and promoted tumour progression." (PMID 29689643, 2018). "G-CSF expression increased after anti-VEGF treatment in LLC tumor lysate, while IL-17A expression was low." (PMID 29707135, 2018). "Specifically, the authors showed that miR-22 decreased the production of IL-6, which in turn, inhibited the polarization of Th17 and the expression of IL-17A, finally promoting tumor growth." (PMID 30443251, 2018). "Inhibition of IL-17A and the Th17 stabilizing cytokine IL-23 inhibited intestinal hyperplasia and tumor formation in ApcMin/+ mice arguing in favor of a cytokine-dependent mechanism of this carcinogenesis model." (PMID 28881611, 2017). "IL-17A levels were significantly increased in tumor-bearing mice treated with PBS or control IgG (p < 0.05) as compared to wild-type mice." (PMID 27935862, 2017). "In conclusion, our study established a pro-tumor role of IL-17A that has important implications for ER-negative breast cancer and laid the foundation for further exploration of the potential of IL-17A as a target in cancer immunotherapy." (PMID 27935862, 2017). "We found that 400 mg IL-17A Ab/mouse prolonged the survival time of tumor-bearing mice; however, high-dose antibody injections can cause serious side effects." (PMID 27935862, 2017). "At 7 days after inoculation, tumor-bearing mice were treated with anti-IL-17A Ab, control IgG, or PBS four times at 1-week intervals." (PMID 27935862, 2017). "IL-17A was intensely expressed in the intra-tumor and peri-tumor areas of cancer tissues in 4NA group, and the expression was reduced by CMP treatment." (PMID 29212184, 2017). "IL-17A is a cytokine produced by immune cells to promote tumor growth via up-regulation of IL-6, IL-8, G-CSF, VEGF, MMP-2, MMP-9, and p-STAT3 expression in cancer cells and tissues." (PMID 29212184, 2017). "The absence of miR-21 also reduced the expression of inflammatory cytokines (IL-6, IL-23, IL-17A and IL-21) and attenuated the proliferation of tumour cells." (PMID 28099146, 2017). "In dealing with the controversy, the role of IL-17A in tumorigenesis has been postulated to depend on multiple factors including the specific tumor type and the cellular sources of IL-17A." (PMID 28562353, 2017). "Recent studies have highlighted the mechanisms by which the cytokines secreted by inflammatory cells and regulated by the transcription factor NF-κB such as TNF-α, IL-6 and IL-17A stimulate tumor development and progression." (PMID 28881574, 2017).
tumor (continued). "IL-17A was shown to promote angiogenesis by upregulation of pro-angiogenic factors secreted from tumor cells, subsequently promoting carcinogenesis." (PMID 28881611, 2017). "To this end, we characterized TILs in anti-IL-17A Ab-treated tumors by flow cytometry to determine the potential roles of anti-IL-17A Ab-mediated tumor suppression in ER-negative breast cancer models." (PMID 27935862, 2017). "Ablation of IL-23 or IL-23R attenuated the expression of IL-17A and reduced cell proliferation and tumor load." (PMID 28852270, 2017). "Our results show that L-4F treatment significantly inhibited tumor progression, decreased inflammatory cell infiltration in tumor tissues, and reduced percentages of IL-17A-, IL-6-, GM-CSF- and IL-1β-producing cells to varying degrees in tumor tissues." (PMID 29245934, 2017). "In the tumor microenvironment, IL-17A promotes neutrophil recruitment and DNA damage in local tissue by secreting radical oxygen species." (PMID 28399860, 2017). "Various molecular and cellular mechanisms mediate the pro-tumor and/or anti-tumor functions of IL-17A." (PMID 28562353, 2017). "On the other hand, L-4F inhibited both the cytokines (IL-4 and IL-17A) producing cells in tumor tissues and the important signaling molecules (phosphorylation of ERK and STAT3)." (PMID 29245934, 2017). "Anti-tumor agents, like resveratrol and ursolic acid, were also reported to inhibit IL-17A production." (PMID 29212184, 2017). "It is feasible to inhibit tumor cell growth by decreasing PDL1 expression with IL-17A Ab in the tumor microenvironment." (PMID 27935862, 2017). "IL-17A promotes tumor cell survival and invasiveness and inhibits the antitumor immune response by interacting with myeloid-derived suppressor cells (MDSCs)." (PMID 27935862, 2017). "Our data demonstrate that tumour-induced Th17 cells progressively transdifferentiate into IL-17A+Foxp3+ and ex-Th17 IL-17AnegFoxp3+ T cells during tumour development." (PMID 28290453, 2017). "Here, we performed this meta-analysis to test overall survival (OS) and disease-free survival (DFS) as outcomes in patients with solid tumor with known IL-17A levels within tumor evaluated by IHC." (PMID 29029520, 2017). "In summary, these findings prove that CMP and cordycepin can inhibit tumor growth in which IL-17A plays a vital role for cancer cell proliferation." (PMID 29212184, 2017). "We also showed that IL17A is produced by tumor-infiltrating lymphocytes isolated in biopsies from six patients with TN BC." (PMID 28775276, 2017). "The tumor-bearing mice treated with anti-IL-17A had a significantly lower tumor burden than did mice treated with PBS or control IgG (p < 0.05)." (PMID 27935862, 2017). "On the one hand, IL-17A has been shown to induce vascular endothelial growth factor, suppress apoptosis of various tumor cell lines in vitro, and directly promote tumor growth." (PMID 28406993, 2017). "IL-17A was injected to the SBE treated mice from day 9 post H22 inoculation to examine its effect on tumor growth." (PMID 28086772, 2017). "IL-17A is an important proinflammatory cytokine which is frequently elevated in tumor microenvironment." (PMID 29029520, 2017). "Especially, in combination with IL-17A administration B cells showed enhanced tumor killing capability by promoted B-cell migration and higher production of immunoglobulins." (PMID 29050338, 2017). "The relative expression of IL-17A was significantly lower in tumor tissues than in benign tissues (P = 0.036)." (PMID 28537908, 2017). "Because of the high expression of IL-17 receptor chains on tumor cells, IL-17A has direct effects on these cells." (PMID 27935862, 2017). "Specifically, IL-17A can indirectly control tumorigenesis via regulating inflammatory responses, angiogenesis and anti-tumor immunity, and directly influence tumor growth and neoplastic transformation." (PMID 28562353, 2017).
tumor (continued). "It will be interesting in future studies to evaluate what roles IL-17A and other cytokines play in mediating the antitumor effects of RORγ agonists across different tumor models." (PMID 28123897, 2016). "In this study, we investigated the accumulation of CD20+ B cells in the ESCC tumor nests and further addressed the effect of IL-17A on the migration and cytotoxicity of B cells." (PMID 26942702, 2016). "Direct or indirect Stat3 pathway activation by IL-17A promotes the proliferation and progression of various tumors, whereas IL-17A-mediated adaptive and innate immune responses exert anti-tumor effects." (PMID 27462789, 2016). "The proinflammatory cytokine interleukin-17A (IL-17A) is reported to up-regulate tumor invasiveness via ECM degradation by matrix metalloproteinases (MMPs)." (PMID 26850593, 2016). "Th17 cells express the transcription factors RORγt/RORC2 (mouse/human) and RORα, which drive Th17 differentiation and produce pro-inflammatory cytokines, including IL-17A, that modulate the tumor microenvironment." (PMID 27784305, 2016). "Based on literature precedence, IL-17A can be considered to play a vital role in inducing anti-tumor effects including inducing potent tumor killing via TH17." (PMID 27213458, 2016). "Both tumour-suppressing and tumour-promoting functions have been attributed to IL-17A and TH17 cells, and the role of TH17 cells in tumour immunity remains ambiguous." (PMID 27990285, 2016). "Several studies have found higher expression of IL-17A in tumor tissues, such as multiple myeloma, ovarian cancers, gastric cancer and breast cancer." (PMID 26812681, 2016). "Proinflammatory cytokines secreted by Th17 cells such as IL-17A have been shown to impair immune surveillance and promote tumor growth." (PMID 27413254, 2016). "IL-17E, through binding to its own receptor IL-17RB or IL-17RA, shows different properties from IL-17A and IL-17 F in tumor fields." (PMID 27716046, 2016). "In vitro treatment of tumor-specific T cells with RORγ agonists, followed by adoptive transfer to tumor-bearing mice is highly effective at controlling tumor growth while improving T cell survival and maintaining enhanced IL-17A and reduced PD-1 in vivo." (PMID 28123897, 2016). "The tumor-promoting mechanism of Th17 cells is dependent on the production of IL-17A, a pro-inflammatory cytokine, that is known to promote tumor angiogenesis, stimulate tumor cells to produce IL-6, and in some murine models recruit MDSCs within tumors." (PMID 27341128, 2016). "IL-17A, which was increased in tumor tissue, was the only cytokine with altered expression when compared with adjacent uninvolved tissue." (PMID 27014625, 2016). "These receptor chains are broadly expressed in many cell types accounting for the pleiotropic effects of IL-17A on epithelial cells (including transformed tumor cells), endothelial cells, osteoblasts, fibroblasts, and various myeloid cells." (PMID 26783383, 2015). "As to the B16 tumor challenge model, which is adopted in this study, existing reports have concluded that both IL-6 and IL-17A function as anti-tumor factors and can enhance the immune response." (PMID 25826372, 2015). "Inhibition of IL-17A at tumor sites by intratumoral injection of an adenovirus vector expressing siRNA against the mouse IL-17A gene (Ad-si-IL-17) significantly inhibited tumor growth." (PMID 25590298, 2015). "IL-17A produced by Th17 cells promotes tumor growth by inducing angiogenesis, while IL-21 produced by Th17 cells mediates antitumor effects including induction of apoptosis." (PMID 26478573, 2015). "The lack of IL-17A gene expression in the R-Ras KO mice persisted at the 19-week time point when tumours and elevated IL-17A mRNA levels were detected in the WT mice." (PMID 26133397, 2015). "IL-17A is an important inflammatory cytokine in the development of many inflammatory diseases and it is also frequently detected in tumor microenvironment." (PMID 25250801, 2014).